ORC3 (origin recognition complex subunit 3)
Description:
Component of the origin recognition complex (ORC) that binds origins of replication. DNA-binding is ATP-dependent. The specific DNA sequences that define origins of replication have not been identified yet. ORC is required to assemble the pre-replication complex necessary to initiate DNA replication. Binds histone H3 and H4 trimethylation marks H3K9me3, H3K27me3 and H4K20me3.
Synonyms: LATHEO; ORC3L; IMAGE50150
Tractability: Small molecule: a structure with a bound ligand is known. PROTAC: UniProt records ubiquitination sites on it; ubiquitination databases record sites on it; its protein half-life has been measured.
Gene: Protein-coding gene on chromosome 6 (87,590,067 to 87,677,823, forward strand). Ensembl gene ENSG00000135336.
Subcellular location: Nucleus; Chromosome
Subcellular location (Human Protein Atlas): Nucleoplasm
Pathways (Reactome):
DNA Replication: Activation of the pre-replicative complex; Assembly of the ORC complex at the origin of replication; Assembly of the pre-replicative complex; CDC6 association with the ORC:origin complex; Orc1 removal from chromatin
Cell Cycle: Activation of ATR in response to replication stress; E2F-enabled inhibition of pre-replication complex formation
Gene Ontology:
Molecular function: protein binding; DNA replication origin binding; DNA binding
Biological process: DNA replication initiation; regulation of DNA replication; DNA replication
Cellular component: chromatin; chromosome; chromosome, telomeric region; nuclear origin of replication recognition complex; nucleoplasm; nucleus; origin recognition complex; DNA replication preinitiation complex; nuclear pre-replicative complex
Genetic constraint (gnomAD): Loss-of-function variants: 9 observed, 12.47 expected, observed/expected ratio (o/e) 0.72, 90% interval 0.43 to 1.26. The upper end of that interval is the gene's LOEUF score, 1.26, which puts it in group 5 of 6, group 1 being the genes least tolerant of losing a copy. Missense variants: 165 observed, 157.42 expected, observed/expected ratio (o/e) 1.05, 90% interval 0.92 to 1.19. Synonymous variants: 61 observed, 61.37 expected, observed/expected ratio (o/e) 0.99, 90% interval 0.81 to 1.23.
Homologues: Orthologues: chimpanzee ORC3 (99% identical), macaque ORC3 (97% identical), rabbit ORC3 (91% identical), pig ORC3 (90% identical), dog ORC3 (89% identical), guinea pig ORC3 (88% identical), rat Orc3 (83% identical), mouse Orc3 (80% identical), tropical clawed frog orc3 (65% identical), zebrafish orc3 (51% identical), Drosophila melanogaster Orc3 (33% identical).
Diseases named in the same sentence as ORC3 in open-access papers:
ORC3 is named in the same sentence as 10 diseases in open-access papers, as found by Europe PMC text mining. Sharing a sentence is not in itself a finding about the gene and the disease. The quoted sentences say what the papers report.
hemorrhage (1 paper, 2013). Loss of blood from the vascular compartment to the exterior or into nonvascular body space as a result of rupture or severance of the blood vessels. "In addition, we also consistently observed significant, although also milder, hemorrhage near the midline of orc3/hGFAP-cre mutant cortices (unpublished data)." (PMID 23349620, 2013).
lung carcinoma (1 paper, 2023). "The lung cancer dataset showed that the DNA alteration percentages of the ORC complex were 1.9% (ORC1), 1.7% (ORC2), 1.5% (ORC3), 1.2% (ORC4), 2.2% (ORC5), and 1.4% (ORC6)." (PMID 36205357, 2023).
Meier-Gorlin syndrome (1 paper, 2013). "Strikingly, a mutation found in patients with Meier-Gorlin syndrome maps to a highly-conserved C-terminal segment in Orc6, destabilizing the interaction of Drosophila and human Orc6 with both Orc3 alone and with the core Orc1–5 subcomplex." (PMID 24137536, 2013).
prostate carcinoma (1 paper, 2017). A carcinoma that arises from epithelial cells of the prostate gland. "Our data suggest that also ORC3 and PM20D2 may represent CYCLOPS genes that could potentially serve as future drug targets in prostate cancers harboring large 6q deletions." (PMID 29312579, 2017).
tumor (3 papers, 2020 to 2023). "Validation studies of the expression levels of ORCs in HCC were performed in the GEPIA database, which indicated that ORC1 and ORC3-6 presented high levels of expression in tumor tissues, while ORC2 showed the opposite results." (PMID 32194798, 2020). "Our results indicated that the expression of ORC1, ORC2, ORC3, ORC4, ORC5, and ORC6 was different in the seven common types of tumor‐infiltrating immune cells, such as B cells, CD4 T cells, CD8 T cells, NK cells, macrophages, endothelial cells, and cancer‐associated fibroblasts." (PMID 36205357, 2023).
cancer (2 papers, 2021 to 2023). A tumor composed of atypical neoplastic, often pleomorphic cells that invade other tissues. "For instance, both origin recognition complex 3 (ORC3) and suppressor of cancer cell invasion (SCAI) saw increased inclusion of poison cassette exons predicted to terminate their respective ORFs and/or promote mRNA degradation via nonsense-mediated mRNA decay." (PMID 34375640, 2021).
ORC3 also shares sentences with these, for which no sentence is quoted: breast carcinoma (1 paper); glioma (1); Gorlin syndrome (1); intrahepatic cholangiocarcinoma (1).